CST3 (cystatin C)
Diseases named in the same sentence as CST3 in open-access papers (continued):
Sharing a sentence is not in itself a finding about the gene and the disease.
placental abruption (2 papers, 2016 to 2025). Vaginal bleeding preceding the 20th week of gestation. "As the correct proportion of cathepsin B and cystatin C is crucial for an uncomplicated implantation and further placentation, an important role of these enzymes in placental abruption may be considered." (PMID 26904684, 2016). "This study aimed to construct a nomogram model for predicting placental abruption in patients with severe pre-eclampsia based on serum adiponectin (APN), cystatin C (Cys-C), and D-dimer, and to validate its predictive efficacy and clinical application value." (PMID 41229519, 2025).
polycystic ovary syndrome (2 papers, 2013 to 2023). A disorder that manifests as multiple cysts on the ovaries. "In our study, an inflammatory mechanism does not seem to be involved in the association between cystatin C and polycystic ovary syndrome." (PMID 24639696, 2013).
primary Sjögren’s syndrome (2 papers, 2023 to 2025). "Type 1 conventional dendritic cells (cDC1) most highly express cystatin 3 (CST3), which in Sjögren syndrome is decreased." (PMID 37138096, 2023).
prion disease (2 papers, 2015 to 2019). A transmissible disease that is caused by a protein that is able to induce abnormal folding of normal cellular proteins, leading to characteristic spongiform brain changes, which are associated with neuronal loss without an inflammatory response. "Some DEGs are found to be related to prion disease, including Ywhag, Mt2, Serpinh1 and Cst3." (PMID 31767948, 2019).
renal hypertension (2 papers, 2021 to 2025). Hypertension caused by the kidney's hormonal response to narrowing or occlusion of the renal arteries. "Their levels correlated positively with disease activity (SLEDAI), inflammation (CRP), and renal damage indicators (BUN, Scr, cystatin C, urine α1-MG, and renal hypertension)." (PMID 40988967, 2025). "As shown in the forest plots, CLR, NLR, and FAR were positively correlated with SLEDAI, BUN, SCr, cystatin C, urine α1-MG, and renal hypertension (all p<0.05)." (PMID 40988967, 2025). "These included serum markers, such as SCr, BUN, cystatin C, GFR, and renin, a marker related to renal hypertension." (PMID 33805740, 2021).
retinal degeneration (2 papers, 2023 to 2025). Degeneration of the retina. "The results showed that proteins like CST3, C9, and ITM2B, among others, are associated with retinal degeneration while proteins such as COL1A2, IGFBP2, and AGT, among others, are associated with diabetic complications." (PMID 37884923, 2023). "Elucidating the molecular pathways linking cystatin C to retinal degeneration could provide new therapeutic targets for AMD prevention and treatment." (PMID 41301918, 2025). "Moreover, elucidating the molecular pathways linking cystatin C to retinal degeneration may open new therapeutic avenues, providing opportunities for targeted interventions aimed at modulating cystatin C-related mechanisms in AMD pathogenesis." (PMID 41301918, 2025).
sickle cell anaemia (2 papers, 2023 to 2024). "At present, the cystatin-based CKD-EPI equation is used to estimate GFR in adults with sickle cell disease, as it is less biased and more accurate than the combined equation with creatinine and cystatin C when compared with GFR measured using iohexol." (PMID 39329176, 2024).
spinal cord injuries (2 papers, 2020 to 2025). "A multicentre retrospective study was performed to observe the changes in serum cystatin C (CysC) levels in patients with acute spinal cord injury (SCI)." (PMID 31586154, 2020).
ST Elevation Myocardial Infarction (2 papers, 2016 to 2017). A myocardial infarction that produces elevation in the ST segments of the ECG. "The increase in serum cystatin C levels after ST-elevation myocardial infarction could also be a predictor of medium-term major adverse cardiovascular events." (PMID 29312646, 2017).
stomach cancer (2 papers, 2019 to 2025). "Another member of this family, cystatin C, was shown to be expressed in stomach neoplasms." (PMID 31391093, 2019).
thrombotic microangiopathy (2 papers, 2022 to 2025). The syndromes of microangiopathic hemolytic anemia, thrombocytopenia, and variable signs of organ impairment, due to platelet aggregation in the microcirculation. "Further assessment of correlations between cfDNA levels and markers of AKI (i.e., serum creatinine (SCr), cystatin C, neutrophil gelatinase–associated lipocalin (NGAL)), biomarkers of thrombotic microangiopathy and of inflammation in patients' serum was performed." (PMID 35497096, 2022).
tuberculosis (2 papers, 2017 to 2025). A chronic, recurrent infection caused by the bacterium Mycobacterium tuberculosis. "Concentrations of NGAL and cystatin C, both early markers of renal injury, were increased in patients with HIV-tuberculosis and associated with decreased survival time." (PMID 28363198, 2017). "A study found that 5′-NT, uric acid, globulin, creatinine, cystatin C, and AST were key predictors for evaluating the therapeutic effect of tuberculosis." (PMID 40559721, 2025). "Patients with HIV-tuberculosis who died presented with higher concentrations of TFF3, cystatin C, and NGAL." (PMID 28363198, 2017). "Markers of intestinal damage (TFF3) and kidney injury (cystatin C and NGAL) were increased in patients with HIV-tuberculosis compared with HIV-infected controls." (PMID 28363198, 2017).
type 2 diabetic nephropathy (2 papers, 2017 to 2023). "For type 2 diabetic nephropathy, it is reported that urinary cystatin C and NAP (nonalbumin protein) could reflect the progression of type 2 diabetic nephropathy." (PMID 28401167, 2017).
Wilms tumor (2 papers, 2021 to 2022). An embryonal neoplasm characterized by the presence of epithelial, mesenchymal, and blastema components. "This signal colocalises with biomarkers of kidney function (cystatin C, creatinine, urate, and urea) and a SNP in the 95% credible set, rs807624, has previously been reported as associated with Wilms tumor, a pediatric kidney cancer rarely seen in patients over the age of five." (PMID 34128465, 2021).
acromegaly (1 paper, 2017). Acromegaly is an acquired disorder related to excessive production of growth hormone (GH) and characterized by progressive somatic disfigurement (mainly involving the face and extremities) and systemic manifestations. "Consistent with our result, a relationship between EAT and serum cystatin C was demonstrated in subjects with acromegaly." (PMID 28922364, 2017).
acute aortic dissection (1 paper, 2024). "Compared with urea and creatinine, the serum cystatin C concentration increases earlier when the kidney is injured, and it is a useful predictor of short-term mortality and AKI in acute aortic dissection patients." (PMID 38918723, 2024).
Age-related cataract (1 paper, 2022). A type of cataract (opacification of the lens) that forms during the course of aging. "They concluded with contradictory results that increasing cystatin C levels was associated with an increased risk of age-related cataracts, especially cortical and posterior subcapsular subtypes." (PMID 36568781, 2022).
Airway obstruction (1 paper, 2016). Obstruction of conducting airways of the lung. "Also, the cathepsin S/cystatin C ratio (p = 0.02, OR = 0.87) and age (p = 0.001, OR = 3.02) correlated to severe airway obstruction." (PMID 27994288, 2016).
Arrhythmia (1 paper, 2021). Any cardiac rhythm other than the normal sinus rhythm. "The nomogram constructed by LDH, CHE, Cystatin C, and arrhythmia can assess the risk of postoperative delirium in patients undergoing hip and knee arthroplasty." (PMID 34901277, 2021). "Univariate analyses showed that operation duration (P < 0.2), LDH (P < 0.2), CHE (P < 0.2), Cystatin C (P < 0.2), arrhythmia (P < 0.2), NE (P < 0.2), TBil (P < 0.2), DBil (P < 0.2), Cr (P < 0.2), and Mg (P < 0.2) were significant." (PMID 34901277, 2021). "Our study found that preoperative arrhythmia, operation duration, increase of LDH and Cystatin C, and decrease of CHE were independent risk factors for delirium after elderly orthopedic hip and knee arthroplasty." (PMID 34901277, 2021). "Our study revealed that arrhythmia, operation duration, the increase of lactate dehydrogenase and Cystatin C, and the decrease of cholinesterase were reliable factors for predicting postoperative delirium after elderly hip and knee arthroplasty." (PMID 34901277, 2021). "LDH, CHE, Cystatin C, and arrhythmia were used to construct a nomogram to predict the POD." (PMID 34901277, 2021). "In this retrospective study, we found that preoperative arrhythmia, operation duration, increase of LDH and Cystatin C, and decrease of CHE were independent risk factors for POD; simultaneously, the nomogram was a reliable tool for clinical decision-makers to predict the development of POD." (PMID 34901277, 2021).
asthenozoospermia (1 paper, 2024). "In cases of asthenozoospermia, protein tyrosine phosphatase non-receptor type 14 (PTPN14) shows dysregulation, while cystatin-C (CST3) levels are reduced." (PMID 39685846, 2024).
Autoimmunity (1 paper, 2025). The occurrence of an immune reaction against the organism's own cells or tissues. "Our data showed that MRL/lpr mice displayed significantly lower spleen and kidney weight indices and higher levels of serum dsDNA antibodies, nRNP/Sm antibodies, urine albumin/creatinine ratio, and serum cystatin C, suggesting a damaged kidney function and high level of autoimmunity." (PMID 40761479, 2025).
Becker muscular dystrophy (1 paper, 2021). Becker muscular dystrophy (BMD) is a neuromuscular disease characterized by progressive muscle wasting and weakness due to degeneration of skeletal, smooth and cardiac muscle. "Cystatin C may be a useful and minimally invasive biomarker for determination of renal function, particularly suitable in Duchenne or Becker Muscular Dystrophy patients, but certainly also applicable for other neuromuscular patients." (PMID 34630276, 2021).
benign ovarian tumours (1 paper, 2013). "However, in ascetic fluids cystatin C increased versus control serum level (p<0.05), as well as benign ovarian tumours (p<0.05)." (PMID 23986888, 2013).
brain injury (1 paper, 2014). Acute and chronic (see also brain INJURIES, CHRONIC) injuries to the brain, including the cerebral hemispheres, CEREBELLUM, and brain STEM. "Here we describe the effect of cystatin C intracerebroventricular administration in rats prior to inducing a traumatic brain injury." (PMID 24714089, 2014).
Candidemia (1 paper, 2022). A form of invasive candidiasis where species of CANDIDA are present in the blood. "The associations of UA and cystatin C (CysC) levels with diagnosis and prognosis of candidemia were determined." (PMID 35794998, 2022).
carcinoma in situ (1 paper, 2010). "Absence of cystatin C in these transgenic mice resulted in more progression of dysplasia to carcinoma in situ on the face, ear, chest, and tail." (PMID 21085595, 2010).
cerebral embolism (1 paper, 2022). "Patients with cardiogenic cerebral embolism were enrolled in the study, and the results demonstrated Cystatin C was associated with END within 3 days of cardiogenic cerebral embolism." (PMID 35711907, 2022).
chronic pancreatitis (1 paper, 2025). A chronic inflammatory process causing damage and fibrosis of the pancreatic parenchyma. "These preliminary results could not confirm that genetic variants of the CST3 gene play a role in the pathogenesis of chronic pancreatitis." (PMID 39962054, 2025). "Notably, Cst3−/− mice did not develop spontaneous forms of acute or chronic pancreatitis, even in the presence of higher CTSB activity within the secretory compartment." (PMID 39962054, 2025).
chronic viral hepatitis C (1 paper, 2022). "Serum cystatin C is increased with the progression of chronic viral hepatitis C as a potential marker for liver inflammation and fibrosis." (PMID 36466932, 2022).
CNS Lymphoma (1 paper, 2018). "In this report, we describe two cases where cystatin C was used in conjunction with creatinine to inform MTX dosing for CNS lymphoma." (PMID 29780646, 2018).
colorectal polyps (1 paper, 2025). "Cystatin C, TG, and LDL-C concentrations were higher (P < 0.001) in patients with colorectal polyps than in controls." (PMID 40520898, 2025). "To explore the diagnostic value of the NLR, mean corpuscular haemoglobin (MCH), MCH concentration (MCHC), cystatin C, TG, LDL-C, CEA, P. gingivalis, F. nucleatum, P. intermedia, R. gnavus, B. ovatus, and P. distasonis in colorectal polyps, we plotted ROC curves." (PMID 40520898, 2025).
Disseminated intravascular coagulation (1 paper, 2022). Disseminated intravascular coagulation is characterized by the widespread activation of coagulation, which results in the intravascular formation of fibrin and ultimately thrombotic occlusion of small and midsize vessels. "The prediction model consisted of 11 variables, including vasopressor, mechanical ventilation, disseminated intravascular coagulation, admission heart rate, hemoglobin, baseline cystatin C, phosphorus, total bilirubin, lactic dehydrogenase, prothrombin time, and procalcitonin." (PMID 36203572, 2022).
dry eye (1 paper, 2024). "A study comparing the tear fluid from pSS patients with that of non-SS dry eye subjects revealed upregulated protein metabolism involving MMP8, SERPINB5, RPLP2, CSTB, and CST3 in pSS patients compared to controls." (PMID 39408709, 2024).
dysplasia (1 paper, 2010). A usually neoplastic transformation of the cell, associated with altered architectural tissue patterns. "Therefore, absence of cystatin C enhanced dysplasia to SCC progression in site-matched skin in the K14-HPV16 transgenic mice." (PMID 21085595, 2010).
End Stage Liver Disease (1 paper, 2019). Final stage of a liver disease when the liver failure is irreversible and LIVER TRANSPLANTATION is needed. "Substitution of cystatin C for creatinine significantly improved the model for end-stage liver disease (MELD) score accuracy for mortality prediction." (PMID 31601879, 2019).
endometrial carcinoma (1 paper, 2025). A malignant tumor arising from the epithelium that lines the cavity of the uterine body. "The diversity increased greatly from benign to high-grade endometrial carcinoma and the benign condition, low-grade endometrial carcinoma and high-grade clustered into CST1, CST 2, and both CST3 and CST4, respectively." (PMID 40041148, 2025).
endophthalmitis (1 paper, 2025). An infectious process affecting the internal structures of the eye. "In the HVIP1 vitreous, there were a number of significant correlations identified: CRP/Myoglobin, IGFBP-4/SAA, IGFBP-4/VCAM-1, and VCAM-1/SAA in the endophthalmitis group; MPO/NGAL, CRP/SAA, and Cystatin C/Myoglobin in controls; and NGAL/MMP-9 in both groups." (PMID 40563988, 2025).
esophageal squamous cell carcinoma (1 paper, 2025). Esophageal squamous cell carcinoma (ESCC) is a type of esophageal carcinoma (EC) that can affect any part of the esophagus, but is usually located in the upper or middle third. "This study aimed to explore the relationship between pretreatment serum creatinine to cystatin C ratio (CCR) and prognosis in patients with esophageal squamous cell carcinoma (ESCC) receiving neoadjuvant immunochemotherapy (NICT)." (PMID 41041331, 2025).
eye tumors (1 paper, 2013). "Increased level of cystatin C in tear fluid seems to be a possible diagnostic factor in the eye tumors studied." (PMID 23984285, 2013). "However, the role of cystatin C in eye tumors has not been studied in detail." (PMID 23984285, 2013).
Fabry disease (1 paper, 2014). Fabry disease (FD) is a progressive, inherited, multisystemic lysosomal storage disease characterized by specific neurological, cutaneous, renal, cardiovascular, cochleo-vestibular and cerebrovascular manifestations. "In an observational, multicentre study of 89 patients (n = 42 females; n = 47 males) with Fabry disease and varying degrees of disease severity, serum Cystatin C levels were measured." (PMID 24886109, 2014). "The authors concluded that Cystatin C is a good and cost-effective prognostic indicator of early renal dysfunction and/or heart failure in Fabry disease." (PMID 24886109, 2014). "The utility of Cystatin C as a biomarker in Fabry disease has also been evaluated." (PMID 24886109, 2014).
Focal glomerulosclerosis (1 paper, 2015). "Renal outcome was measured by glomerular filtration rate, effective renal plasma flow, fractional excretion of sodium, albuminuria, plasma creatinine, and cystatin C. Focal glomerulosclerosis (FGS) incidence was evaluated by renal histology." (PMID 26252578, 2015).
Graves disease (1 paper, 2015). Graves' disease is an autoimmune disorder that leads to overactivity of the thyroid gland (hyperthyroidism).It is caused by an abnormal immune system response that causes the thyroid gland to produce too much thyroid hormones. "Glomerular filtration rate (eGFR) by serum creatinine (eGFRCr) or standardized cystatin C (eGFRCysC) were estimated in Japanese patients with Graves׳ disease (GD) of different sex." (PMID 26793755, 2015).
hematoma (1 paper, 2022). A hematoma is a collection of blood from a vascular structure into an extravascular space. "In this study, hematoma volume was significantly related to platelet count, serum creatinine, and cystatin C, but it was not significantly correlated with age, gender, BMI, hemoglobin level, 24-h urine protein level, GFR, or renal size (long diameter)." (PMID 35781773, 2022).
Hydrocephalus (1 paper, 2025). Hydrocephalus is an active distension of the ventricular system of the brain resulting from inadequate passage of CSF from its point of production within the cerebral ventricles to its point of absorption into the systemic circulation. "In the clinical model, the disease course, serum uric acid, serum cystatin C, and the lateral ventricular temporal horn ratio emerged as independent risk factors for MCI following hydrocephalus." (PMID 41477165, 2025).
hypertrophic cardiomyopathy (1 paper, 2025). A condition in which the myocardium is hypertrophied without an obvious cause. "This study is the first to assess the relationship between serum cystatin-C and all-cause mortality in patients with hypertrophic cardiomyopathy (HCM)." (PMID 41221210, 2025). "However, the prognostic value of cystatin-C remains unidentified in hypertrophic cardiomyopathy (HCM) patients." (PMID 41221210, 2025).
Hyponatremia (1 paper, 2024). An abnormally decreased sodium concentration in the blood. "Hyponatremia, low hemoglobin levels, elevated platelet counts, increased D-dimer levels, and higher cystatin C levels were identified as independent high-risk factors for CALs." (PMID 39877016, 2024). "The figure illustrates that factors such as hyponatremia, low hemoglobin levels, thrombocytosis, elevated D-dimer levels, and elevated cystatin C levels yielded higher scores, significantly increasing the risk of a CAL." (PMID 39877016, 2024).
ileus (1 paper, 2026). Decrease in peristalsis in the absence of a mechanical bowel obstruction. "Of these, the baseline variables ileus, peritoneal carcinomatosis, and cystatin C levels constituted the core set for multivariable analysis." (PMID 42063062, 2026).
interstitial lung disease (1 paper, 2018). A diverse group of lung diseases that affect the lung parenchyma. "First, we analyzed the expression of CST3 and GDF15 in lung tissues of patients with and without interstitial lung disease (ILD)." (PMID 29724997, 2018).
intracerebral hemorrhage (1 paper, 2005). A cerebrovascular disorder characterized by bleeding into one or both cerebral hemispheres including the basal ganglia and the cerebral cortex. "Similarly, sporadic amyloid angiopathy and intracerebral hemorrhage was reported in an elderly man due to cystatin C mutation." (PMID 15904486, 2005). "Similarly, cystatin C mutation in an elderly man was reported to be the cause of amyloid angiopathy and intracerebral hemorrhage." (PMID 15904486, 2005).